NBN (nibrin)
Diseases named in the same sentence as NBN in open-access papers (continued):
Sharing a sentence is not in itself a finding about the gene and the disease.
breast carcinoma (continued). "Promoter and intronic sequence variations of the NBN gene in French Canadian breast cancer cases and healthy controls." (PMID 19523210, 2009). "Exonic sequence variations of the NBN gene in French Canadian breast cancer cases and healthy controls." (PMID 19523210, 2009). "Analysis of NBN cDNA was also performed on a subset of these breast cancer cases and highlighted the presence of two distinct alternative splice events." (PMID 19523210, 2009). "Taken together, heterozygous germline pathogenic alterations in the NBN gene probably do not predispose female carriers to breast cancer, but significantly increase the prostate cancer risk in male carriers." (PMID 36982687, 2023). "Some germline NBN variants have been associated with an increased risk of developing breast cancer; however, no data are available for colon cancer." (PMID 36552003, 2022). "Other genes with moderate, low, or uncertain penetrance that have been implicated in breast cancer, RECQL, RAD51B, ERCC3, MRE11A, RAD51D, BARD1, and NBN, had a yield of 0.3% (n = 7), 0.3% (n = 7), 0.3% (n = 6), 0.3% (n = 6), 0.2% (n = 4), 0.2% (n = 4), and 0.1% (n = 3), respectively." (PMID 35971132, 2022). "However, mutations in other HRR genes, such as ATM, CHEK2, PALB2, NBN, MRE11, and RAD51 paralogs RAD51C and RAD51D also increase cancer risk and are already included in many screening panels for breast cancer." (PMID 36139526, 2022). "The mutations p.Asp95Asn in NBN and p.Lys425Arg in POLE segregated with both breast and ovarian cancer cases; the VUS in MSH6 p.Ser144Ile was identified in the two cases of breast cancer, one of them bilateral, in an HNPCC family." (PMID 32522261, 2020). "For example, CDKN2A, NF1, and NBN were associated with increased risk for breast cancer in the current study, but were not significant in previously published analyses in our smaller cohorts." (PMID 31406321, 2020). "Other NBN variants designated as pathogenic using ACMG/AMP criteria were observed in only 1 case and 3 controls, providing little support for a role of NBN in Japanese unselected breast cancer patients." (PMID 30287823, 2018). "For the moderate-risk homologous recombination repair (HRR) breast cancer genes ATM, BARD1, CHEK2, and NBN, 3.3% (p = 7.2 × 10− 04) of unselected pancreatic cancer cases carried a clearly pathogenic variant, and weighted inclusion of HiP-VUS increased the proportion to 5.1% (p = 2.3 × 10− 08)." (PMID 29945567, 2018). "Carriers of deleterious variants in either ATM, CHEK2, PALB2 or NBN are typically counseled for their risk of breast cancer, but not ovarian cancer risk despite associations in current literature." (PMID 28591191, 2017). "Mutations in NBN, the gene for Nijmegen Breakage Syndrome (NBS), are thought to predispose women to developing breast cancer, but a breast cancer cell line containing mutations in NBN has not yet been described." (PMID 24928521, 2014). "HCC1395 breast cancer cells exhibited reduced NBN protein levels." (PMID 24928521, 2014). "In a search for breast cancer cell lines with deficiencies in the MRN-ATM pathway, and thus defective DNA double strand break response, we here describe the triple-negative breast cancer cell line, HCC1395, as being mutated in the NBN gene." (PMID 24928521, 2014).
breast carcinoma (continued). "Indeed, it has been reported that the BRIP1 and RAD51 pathogenic variants confer at least a 6-fold increased risk for OC, but not for breast cancer, in contrast to the NBN and CHEK2 genes." (PMID 30441849, 2018). "Furthermore, this lack of association between NBN germline variants and breast cancer risk was supported by the negative results of the two largest analyses examining germline variants in cancer susceptibility genes in female breast cancer patients." (PMID 36982687, 2023). "Our study’s primary aim was to evaluate the association of common putatively functional SNPs in HRR genes NBN, RAD51, and XRCC3 with RT adverse events in patients with early HER2-positive breast cancer treated with adjuvant RT." (PMID 36139526, 2022). "Mutations in BRCA1/2 genes, especially germline variations, along with other Fanconi anaemia (FA) pathway genes (such as NBN, RAD54L, ATM), are prototypic molecular alterations that confer HRD in breast cancer." (PMID 34465315, 2021). "We also explored the impact of HERV expression in its neighboring breast cancer development genes (BRCA1, CCND1, NBS1/NBN, RAD50, KRAS, PI3K/PIK3CA) and in long non-coding RNA expression (AC060780.1, also known as RP11-242D8.1)." (PMID 33194615, 2020). "The National Comprehensive Cancer Network (NCCN) guidelines for genetic assessment in hereditary breast cancer (version 3.2019) recommends genetic evaluation of ATM, CDH1, CHEK2, NBN, NF1, and PALB2 in addition to BRCA1/2 genes." (PMID 31658756, 2019). "Two double heterozygous breast cancer cases were identified in the TNBC group (one patient was BRCA1/CHEK2 and the other was BRCA1/NBN)." (PMID 26083025, 2015). "In the present study we report on the identification of a breast cancer cell line, HCC1395, that harbors p.R215W in the hemizygous state, and we investigate the functional competence of the mutant NBN protein in this cell line." (PMID 24928521, 2014). "In our previous study we showed that the germline p.I171V mutation in NBN, one of the MRN genes, may be considered as a risk factor in the development of childhood acute lymphoblastic leukemia and solid malignant tumors including breast cancer, larynx and colorectal cancer in adult." (PMID 24093751, 2013). "Breast cancer 1 (BRCA1) and breast cancer 2 (BRCA2) play an important role in the HR repair pathway by interacting with other DNA repair proteins such as Fanconi anemia (FA) proteins, ATM, RAD51, PALB2, MRE11A, RAD50, and NBN." (PMID 35785170, 2022). "Other PVs were identified in genes that have a less clear association with breast cancer such as: BRIP1, NBN, RAD50 and RECQL, but none of these showed significant associations." (PMID 34439310, 2021). "In Poland, 20 founder mutations in BRCA1, BRCA2, CHEK2, PALB2, NBN, RECQL are responsible for the majority of hereditary breast cancer cases in women, but the utility this genes panel has not been tested in men." (PMID 34461861, 2021). "It is interesting that heterozygous mutations in other genes in this pathway (i.e., BRCA1, BRCA2, CHEK2, NBN, ATM) predispose to breast cancer, but a heterozygous mutation in BLM does not appear to be pathogenic for breast cancer." (PMID 31614901, 2019). "We don’t observe significant differences in the allele frequencies between different regions of Poland, i.e., for BRCA1, PALB2, CHEK2, NBN, RECQL, and also for the GEN1 founder p.Lys645Cysfs*29 variant, neither in breast cancer cases nor in controls (for GEN1 data)." (PMID 40649769, 2025). "However, the frequencies of these twenty mutant alleles of BRCA1/2, CHEK2, PALB2, NBN, and RECQL have not been measured in a large series of early-onset breast cancer patients from Poland." (PMID 32824581, 2020).
breast carcinoma (continued). "By applying the CIPHER-HIT to the subtype analysis of Breast cancer, we found that the prioritized genes can be divided into two sub-modules, one contains the members of the Fanconi anemia gene family, and the other contains a reported protein complex MRE11/RAD50/NBN." (PMID 21599985, 2011). "However, the functional analysis by luciferase promoter assay does not support a causative effect of this variant in the breast cancer cell line MCF-7, although a reduction of luciferase expression driven by the NBN promoter can be observed in two other cell lines tested." (PMID 19523210, 2009). "The amplification of PTK2, MYC, NBN, and RAD21 found prognostic biomarkers independent of breast cancer subtype." (PMID 35494043, 2022). "Kaplan–Meier analysis showed that the overall survival rates were significantly lower in breast cancer patients with than without amplification of one of these genes (log rank test; NDRG1, P = 0.0554; UBR5, P = 0.0122; MYC, P = 0.0094; EXT1, P = 0.0103; NBN, P = 0.0030; and COX6C, P = 0.0073)." (PMID 28977883, 2017).
Nijmegen breakage syndrome (60 papers, 2008 to 2026). "Biallelic mutation in the DNA-damage repair gene NBN is the genetic cause of Nijmegen Breakage Syndrome, which is associated with predisposition to lymphoid malignancies." (PMID 37503171, 2023). "Nijmegen breakage syndrome caused by mutations and variants in the NBN gene lead to susceptibility to gastric cancer." (PMID 36672781, 2022). "Nijmegen breakage syndrome is a result of mutations in the nibrin gene and is associated with immunodeficiency." (PMID 34885784, 2021). "In another newborn, with low KREC and diminished TREC as well as microcephaly and dysmorphic features, Nijmegen breakage syndrome was recognized with a variant in the NBN gene typical for the Slavic population." (PMID 33178177, 2020). "NBN, which codes for nibrin, mutated in Nijmegen breakage syndrome, and has a role in the end processing step in NHEJ with Artemis and several other proteins." (PMID 32010653, 2019). "A hypomorphic mutation of NBN in humans is responsible for the chromosomal instability syndrome, Nijmegen Breakage Syndrome, in which radiosensitivity, immunodeficiency and early development of haematological malignancy are major features." (PMID 30440001, 2018). "Genetic analyses were performed and revealed a PDGFRB gene c.1681C>A missense heterozygous germline mutation, high PDGFRβ phosphokinase activity within the tumor and the heterozygous germline Slavic Nijmegen breakage syndrome 657del5 mutation in the NBN gene." (PMID 28183292, 2017). "Historically, biallelic germline mutations in NBN have been associated with Nijmegen Breakage syndrome (NBS), a rare autosomal recessive disorder associated with immunodeficiency, dysmorphic features, and high risk of lymphoid malignancy." (PMID 26484312, 2015). "KPNA2 has a role in nucleocytoplasmic transport and is responsible for the import, via its nucleus localization sequence, of NBN, the DNA repair gene mutated in Nijmegen breakage syndrome." (PMID 24892279, 2014). "Nijmegen breakage syndrome (NBS) is caused by mutations in NBN and is characterised by microcephaly, cell cycle checkpoint defects and ionizing radiation sensitivity." (PMID 24637776, 2014). "The relatively high prevalence of the Slavic founder mutation (c.657_661del5) in the NBN gene, particularly in Western regions of Ukraine, likely explains the predominance of Nijmegen breakage syndrome in our cohort and was similarly confirmed in the pilot screening phase." (PMID 41459527, 2025). "Heterozygous carriers of the NBN c.657del5 mutation (which is found in homozygous state in more than 90% of patients with Nijmegen breakage syndrome) who also carry two copies of the NBN polymorphism p.E185Q (GG allele) were shown to be at increased risk for breast and prostate cancers." (PMID 33194896, 2020). "Nijmegen Breakage Syndrome is a disease caused by NBN mutations." (PMID 27050272, 2016). "Mutations within the NBN gene are responsible for the Nijmegen breakage syndrome (NBS)." (PMID 25485873, 2014). "Mutations in NBN or ATM result in Nijmegen Breakage Syndrome and Ataxia telangiectasia." (PMID 23935957, 2013). "In humans, biallelic hypomorphic mutations in NBN lead to Nijmegen breakage syndrome (NBS), an autosomal recessive genetic disease characterised by extreme radiosensitivity coupled with growth retardation, immunoinsufficiency and a very high risk of malignancy." (PMID 19412544, 2009). "Nijmegen Breakage Syndrome (NBS) is a rare autosomal recessive genetic disorder caused by mutations within nibrin (NBN), a DNA damage repair protein." (PMID 35269426, 2022). "NBN is mutated in patients with Nijmegen breakage syndrome (NBS), and cells from NBS patients are hypersensitive to IR." (PMID 33898418, 2021). "Homozygous or compound heterozygous variants within the NBN gene are associated with the autosomal recessive Nijmegen breakage syndrome (NBS) whereby an increased cancer susceptibility for heterozygous carriers of certain NBN variants has been reported." (PMID 33840814, 2021).
Nijmegen breakage syndrome (continued). "Deletions, single point mutations, or altered expression of the NBN gene have been shown to cause Nijmegen Breakage Syndrome (NBS), aplastic anemia, and an increased risk of certain types of cancer." (PMID 32668560, 2020). "Nijmegen breakage syndrome (NBS) is an autosomal-recessive disease caused by mutations of the NBN gene on chromosome 8q21." (PMID 32010653, 2019). "Nijmegen breakage syndrome (NBS) is an autosomal recessive disease caused by biallelic mutations in NBN, a gene that encodes nibrin, a protein involved in DNA repair and cell cycle checkpoint regulation." (PMID 29238724, 2017). "Nijmegen Breakage Syndrome (NBS) is associated with cancer predisposition, premature aging, immune deficiency, microcephaly and is caused by mutations in the gene coding for NIBRIN (NBN) which is involved in DNA damage repair." (PMID 28790359, 2017). "Defects in the NBN gene result in a rare autosomal recessive disorder known as Nijmegen breakage syndrome (NBS) characterised by microcephaly and a predisposition to cancers including gliomas." (PMID 25026297, 2014). "The NBN gene underlies Nijmegen Breakage Syndrome (NBS), which is most prevalent in Eastern Europe due to a Slavic founder mutation." (PMID 24025454, 2013). "Not surprisingly, therefore, NBN is an essential gene, however, individuals with hypomorphic mutations in the NBN gene suffer from the autosomal recessive genetic disorder, Nijmegen Breakage Syndrome (NBS, MIM 251260)." (PMID 19412544, 2009). "While the NBN (NBS1) gene is classically associated with autosomal recessive Nijmegen breakage syndrome (NBS), heterozygous carriers of pathogenic NBN variants may also have an elevated cancer risk." (PMID 41528496, 2026). "Genetic disorders such as ataxia-telangiectasia (AT) and Nijmegen breakage syndrome result in extreme radiosensitivity due to defects in key DDR proteins such as ataxia-telangiectasia-mutated kinase (ATM) and nibrin (NBN)." (PMID 40282189, 2025). "In a distinct context, mutations in the Nibrin gene (NBS1) impair DNA damage response and genomic stability, leading to Nijmegen breakage syndrome." (PMID 40362410, 2025). "Nijmegen breakage syndrome (NBS), caused by mutations in the NBN gene, also results in genomic instability, increased cancer risk, and shortened telomeres." (PMID 39126110, 2024). "Our data highlights insights into how hypomorphic mutations within NBN alters neurogenesis in NBS patients, thus providing a proof of concept that iPSC-derived cerebral organoids are a valuable tool which enable research into DNA damage-related disorders such as Nijmegen Breakage Syndrome." (PMID 35269426, 2022). "Increased expression of NBN genes in breast and ovarian cancer cells can induce chemoresistance and poor prognosis, and mutations in NBN can also cause Nijmegen breakage syndrome (NBS), leading to low immune function and abnormal lymphocyte function in patients." (PMID 35840978, 2022). "The patient was diagnosed with Nijmegen breakage syndrome as genetic test confirmed homozygotic deletion c.657_661delACAAA in the NBN gene." (PMID 32843899, 2020). "Nijmegen breakage syndrome (NBS) patients harbour NBN mutations, the product of which, nibrin, is involved in recognising DNA-DSB." (PMID 27717373, 2016). "Hypomorphic mutations in NBN lead to the Nijmegen Breakage Syndrome (NBS, OMIM 251260) a rare autosomal recessive disorder associated with growth retardation, immunodeficiency, neurological defects, radiosensitivity and tumor predisposition, including astrocytomas and medulloblastomas." (PMID 23935957, 2013). "Hypomorphic, biallelic mutations in the MRE11, RAD50 and NBN genes are linked to recessive genetic conditions, ataxia telangiectasia like disorder (AT-LD), NBS-like and Nijmegen breakage Syndrome (NBS), respectively, some of which are characterized by increased risk of cancer." (PMID 24093751, 2013).